LEP (leptin)
Diseases named in the same sentence as LEP in open-access papers (continued):
Sharing a sentence is not in itself a finding about the gene and the disease.
glomerulosclerosis (19 papers, 2011 to 2025). A hardening of the kidney glomerulus caused by scarring of the blood vessels. "Renal disease has been associated with obese individuals, and increased TGF-β and glomerulosclerosis have been reported in patients with high circulating leptin levels." (PMID 24167814, 2013). "Glomerular lesions (glomerulosclerosis) and albuminuria are observed in early stage kidney disease and are associated with metabolic disorders, such as reduced adiponectin levels and lipolysis and increased leptin levels and lipogenesis." (PMID 39412511, 2024). "Additionally, higher leptin concentration, mainly produced by the adipose tissue, affects endothelial cells in a paracrine fashion, ultimately causing glomerulosclerosis and proteinuria." (PMID 25210651, 2013). "In contrast, leptin promotes glomerulosclerosis and fibrosis by triggering transforming growth factor‐β1 synthesis." (PMID 38632706, 2024). "Leptin promotes TGFβ-1 release and type IV collagen and fibronectin production in the glomerulus, leading to proteinuria and glomerulosclerosis." (PMID 36726470, 2022). "Third, leptin, a cofactor in transforming growth factor-beta activation, promotes renal endothelial cell proliferation, and subsequently glomerulosclerosis." (PMID 35619087, 2022). "Recent animal studies have reported that infusion of recombinant leptin into normal rats for 3 weeks fosters the development of glomerulosclerosis." (PMID 22666590, 2012). "Leptin is involved in the development of glomerulosclerosis through a paracrine TGF-β pathway (between glomerular endothelial and mesangial cells) that promotes the deposition of extracellular matrix, proteinuria, and, eventually, glomerulosclerosis." (PMID 22567283, 2012). "Other studies also reported that long-term leptin stimulation increased the expression of type 1 and type 4 collagen also in mesangial cells, as well as urinary protein excretion in a blood pressure-independent manner due to glomerulosclerosis progression." (PMID 34298949, 2021). "Leptin stimulates glomerular endothelial cells proliferation and transforming growth factor-β1 expression/secretion, a profibrinogenic cytokine and contributor to glomerulosclerosis development." (PMID 32315336, 2020). "Leptin induces the synthesis of type 1 collagen in mesangial cells, as well as type 4 collagen in glomerular endothelial cells contributing to extracellular matrix deposition, glomerulosclerosis, and proteinuria." (PMID 23320148, 2012). "Infusion of leptin into normal rats fosters development of glomerulosclerosis and proteinuria." (PMID 21304902, 2011). "In a rat model without pre‐existing CKD, leptin infusion was associated with the development of glomerulosclerosis and proteinuria after 3 weeks, suggesting that leptin could upregulate surface TGF‐β2 receptors through signal transduction pathways." (PMID 40226862, 2025). "Thus, leptin antagonism may directly protect from the development of glomerulosclerosis and renal injury." (PMID 38031726, 2023). "The binding of leptin to renal endothelial cells leads to TGF-β production, which can further promote collagen production by mesangial cells, leading to fibrosis and glomerulosclerosis." (PMID 38031726, 2023). "In normal rat populations, infusion of leptin was found to promote glomerulosclerosis and proteinuria, however studies in humans is lacking." (PMID 33976959, 2021).
influenza (19 papers, 2020 to 2025). An acute viral infection of the respiratory tract, occurring in isolated cases, in epidemics, or in pandemics; it is caused by serologically different strains of viruses (influenzaviruses) designated A, B, and C, has a 3-day incubation period, and usually lasts for 3 to 10 days. "Deng and colleagues showed that low serum leptin levels in young and elderly healthy subjects are associated with lower antibody responses to influenza and hepatitis B (HBV) vaccines." (PMID 39859575, 2025). "Across healthy cohorts, lower baseline leptin associates with weaker serologic responses to influenza and hepatitis B. Leptin promotes mouse/human TFH differentiation and IL-21 production via the STAT3-mTOR axis." (PMID 41516046, 2025). "To better understand the role of leptin in the response to influenza infection, we infected leptin-deficient ob/ob mice with influenza and found that they had a high mortality rate, which was completely prevented by leptin." (PMID 39480494, 2024). "Leptin deficiency caused a profoundly increased susceptibility to influenza infection, which was completely reversed with chronic physiologic leptin replacement prior to infection." (PMID 39480494, 2024). "Here, we report that lower serum levels of the metabolic hormone leptin associate with reduced vaccine responses to influenza or hepatitis B virus vaccines in healthy populations." (PMID 34031386, 2021). "In general, there were few studies focused on the relationship between leptin and influenza vaccines, and the underlying mechanisms were still unclear." (PMID 34745208, 2021). "Morgan and Azzoni reported that impaired leptin signalling is caused by an altered defence response in host for influenza AH1N1 and human immunodeficiency virus (HIV) infections, due to the alterations of the immunologic, metabolic, and endocrine processes." (PMID 33907162, 2021). "Mice with deficient hypothalamic leptin signaling have increased susceptibility to influenza." (PMID 39480494, 2024). "Our data therefore implicate the leptin-AMP-SOC3 axis as an important determinant of antiviral immunity in the airway that may drive susceptibility to severe influenza infections in morbidly obese individuals." (PMID 37857661, 2023). "Similarly, leptin deficiency induced by fasting reduces influenza vaccination-mediated protection for the subsequent infection challenge, which is mostly rescued by leptin replacement." (PMID 34031386, 2021). "Fasting-induced leptin deficiency reduced the protective effects of influenza vaccination in mice and could be specifically reversed by leptin supplementation." (PMID 34696182, 2021). "Additionally, women have higher concentrations of leptin and estrogen normally, with up-regulation of immune response, thereby there were modification effects of gender on the association of SNPs with humoral response to influenza vaccine." (PMID 34745208, 2021). "Leptin administration prior to influenza infection attenuated virus-induced expression of all four of these antiviral immune genes, indicating that leptin is functionally related to attenuated pulmonary type I IFN immune responses." (PMID 37857661, 2023). "Leptin in vitro also induced pro-inflammatory B cells, reduced class switch and influenza vaccine-specific IgG production, and these measures were again comparable to those in B cells from YO and EL individuals." (PMID 35433040, 2022). "To investigate the roles of LEP, LEPR, and PPARG in the humoral immune response to influenza vaccine, we conducted an association study to compare the genotypic frequencies of 11 tag SNPs in these genes between the two groups in the Chinese Han population." (PMID 34745208, 2021). "This study aimed to elucidate the association of SNPs in LEP, LEPR, and PPARG with humoral immune response to influenza vaccine in the Chinese Han population." (PMID 34745208, 2021).
influenza (continued). "Univariate and multivariate logistic regression analyses were used to explore the association of SNPs in LEP, LEPR, and PPARG with humoral immune response to influenza vaccine." (PMID 34745208, 2021). "Alternative measures such as serum leptin levels may more closely align with influenza vaccine seroconversion." (PMID 38917104, 2024). "In this study, we aimed to investigate the potential association of leptin gene (LEP), leptin receptor gene (LEPR), and peroxisome proliferator activated receptor gamma gene (PPARG) polymorphisms with humoral immune response to influenza vaccine." (PMID 34745208, 2021). "Thus, low adiponectin, high leptin levels, and high leptin-resistance contribute to a heightened pro-inflammatory cytokine production in obese patients, and a subsequent blunted immune response to infection by influenza." (PMID 33708775, 2021). "Leptin, a proinflammatory cytokine that is chronically elevated in obese patients, has been identified as a cofactor in the severity and progression of AH1N1 influenza that results in acute lung injury." (PMID 38390960, 2024). "We therefore isolated BAL macrophages from mice and infected them ex vivo with influenza, in the presence or absence of exogenous leptin treatment at 320 μg/ml (mimicking the dose used in vivo) and ten-fold lower 32 μg/ml concentrations." (PMID 37857661, 2023). "Nevertheless, the association between SNPs in LEP, LEPR, and PPARG and influenza vaccine-induced immune response has not been revealed in the Chinese Han population." (PMID 34745208, 2021). "Haplotypes in LEP were not correlated with response to influenza vaccine." (PMID 34745208, 2021). "Moreover, serum leptin levels did not always correlate positively with absolute antibody titers after vaccination or changes in antibody titers in adults vaccinated against influenza or HBV." (PMID 39859575, 2025). "Our results demonstrated that the non-responder groups for both influenza and HBV vaccinations were highly enriched in individuals with low serum leptin." (PMID 34031386, 2021).
leukemia (19 papers, 2006 to 2026). A malignant (clonal) hematologic disorder, involving hematopoietic stem cells and characterized by the presence of primitive or atypical myeloid or lymphoid cells in the bone marrow and the blood. "Most likely due to low leptin, they identified an upregulation of Lepr expression in leukemia cells and activation of downstream signaling routes as main cause leading to inhibition of leukemia initiation and progression." (PMID 32474572, 2020). "Far from being mere bystanders, these lipid-laden cells orchestrate a symphony of signals that influence leukemia’s destiny—balancing cell proliferation and death with surgical precision through a potent brew of adipokines like leptin and adiponectin." (PMID 40563875, 2025). "In stark contrast to leptin’s malignant influence, adiponectin stands as leukemia’s counterforce, a guardian of cellular balance." (PMID 40563875, 2025). "Known to expand BMAT while suppressing leptin levels, fasting emerges as a surprising leukemia disruptor." (PMID 40563875, 2025). "Yet, in leukemia’s complex ecosystem, adiponectin’s voice often goes unheard—overshadowed by the sinister dominance of leptin." (PMID 40563875, 2025). "Among leukemia subtypes, perturbations of various adipokines have been observed, the most thoroughly studied of which are leptin and adiponectin." (PMID 38159164, 2024). "Early intervention and modulation of leptin signaling has the potential to be a promising route for leukemia research." (PMID 35628271, 2022). "Negatively correlated genes such as RUNX1T1 and LEP were reported to have anti-leukemia effects and were also informative for AML prognosis." (PMID 35227274, 2022). "Leptin, the hormone famous for regulating appetite, reveals its darker, insidious side in leukemia." (PMID 40563875, 2025). "The reduction of autocrine of leptin in leukemia cells may negatively feedback regulates the increase of paracrine of leptin from adipose tissues into cancer microenvironment to promote leukemogenesis." (PMID 33485366, 2021). "Additionally, leptin is a pro‐inflammatory, pro‐angiogenic, and pro‐tumorigenic adipokine, which has been shown to stimulate multiple leukemia cell types." (PMID 32706183, 2020). "All in all, the leptin/Lepr axis is an interesting new target for leukemia treatment." (PMID 32474572, 2020). "Leptin may also modulate apoptosis, since it has been reported in leukaemia cell lines that leptin acts as an inhibitor of apoptosis." (PMID 16504019, 2006). "Thus, low serum Leptin levels may negatively affect graft-versus-leukemia (GVL) effects resulting in increased rates of relapse following alloSCT." (PMID 35216457, 2022). "On the other hand, leptin’s potential leukemogenic and anti-apoptotic activity should not be impeded by anti-angiogenesis; this could contribute to the increased rate of childhood leukemia in Down syndrome." (PMID 29587359, 2018). "The overall effect would increase Alzheimer’s risk in DS and might increase leukemia risk but not solid tumor risk if leptin is counteracted by the antiangiogenesis genes on chromosome 21." (PMID 29587359, 2018). "Additionally, a retrospective study that included 20 survivors of childhood leukemia and lymphoma and 20 healthy children revealed that leptin levels were not correlated with BMD and osteocalcin, a marker of bone formation." (PMID 40076690, 2025).
hypogonadotropic hypogonadism (18 papers, 2016 to 2026). Abnormal ovarian or testicular function due to insufficient hormonal stimulation from the hypothalamic-pituitary axis. "Additionally, in leptin-deficient mice, central hypogonadism that can be reversed after leptin treatment has been observed." (PMID 29321542, 2018). "Kyriakou and Skordis stated that the hypogonadotropic hypogonadism observed in β-TM is associated not only with the toxic effect of iron on gonadotroph cells but also with iron toxicity in adipocytes, thereby altering the physiological role of leptin in sexual maturation and fertility." (PMID 27088012, 2016). "Male obesity-associated secondary hypogonadism (MOSH) involves increased levels of leptin, insulin, proinflammatory cytokines, and estrogen, which contribute to functional hypogonadotropic hypogonadism." (PMID 39801930, 2024). "Low IGF-1 levels due to GH resistance, low sex hormone levels due to functional hypogonadotropic hypogonadism, elevated cortisol and low leptin levels all contribute to low bone mass observed in patients with AN." (PMID 32219087, 2020). "Circulating levels of leptin are essential for gonadotropin release and, as such, acute decreases in circulating leptin during fasting or undernourishment lead to hypogonadotropic hypogonadism." (PMID 29905528, 2018).
lung disease (18 papers, 2011 to 2025). "Low leptin production is linked with the pathogenesis of several pulmonary diseases and pulmonary arterial hypertension." (PMID 38610889, 2024). "Deficiency in leptin production has also been associated with susceptibility to pulmonary disease in a mouse model." (PMID 21445235, 2011). "In addition to its metabolic functions, leptin plays important roles in neutrophil and macrophage chemotaxis and association with smoking habits and lung dysfunction has been reported in several lung diseases." (PMID 38111019, 2023). "During symptomatic lung diseases, leptin is the main stimulator of LCK and EGR2 genes, which exacerbates inflammation and activates monocytes, respectively." (PMID 37408184, 2023). "Considering this evidence, recent in vivo and in vitro studies have explored the relationship between levels of these adipokines and lung diseases, revealing that leptin and adiponectin can directly regulate lung inflammation and immune function." (PMID 35806353, 2022). "Several additional studies have investigated the role of leptin in lung disease and injury by utilizing exogenous leptin administration." (PMID 35610699, 2022). "This subgroup demonstrated synchronous lung disease and persistently low circulating leptin levels." (PMID 37737171, 2023). "This hypothesis is in accordance with evidence that leptin and adiponectin have a role in regulating Th17 and Th2 immune responses in lung diseases, in addition to the expression of pro-inflammatory cytokines and NLRP3 activity, as previously discussed." (PMID 35806353, 2022). "Furthermore, the relationship between leptin and lung disease pathogenesis involves excess adipose tissue." (PMID 35806353, 2022). "Such connections include differential leptin and RAGE levels in patients with lung disease, chronic RAGE-mediated inflammation observed in cardiovascular metabolic disruption and neoplasia, and RAGE effects on adipocytokine levels in obese asthmatic mice." (PMID 38732159, 2024). "Leptin-deficient animals show CO2 retention and respiratory depression; leptin administration to these animals increases minute ventilation and improves lung mechanics suggesting that an increase in leptin levels in patients with lung disease may represent a compensatory response to hypoxia." (PMID 22518191, 2012). "As reviewed by Jutant and others, leptin plays a role in several lung diseases such as asthma, COPD, fibrosis, PH and lung cancer, but its role in acute onset of lung disorders, such as lung infections and acute respiratory distress syndrome (ARDS) remain controversial." (PMID 40635334, 2025). "It appears that leptin exerts the opposite effect, inhibiting proliferation and activity of Tregs and promoting that of Th17 cells in patients with COPD and negatively impacting lung disease progression." (PMID 35806353, 2022). "In the present study, the leptin levels in the peripheral blood were not different between patients with MABC lung disease and control subjects, and no change was detected during therapy." (PMID 25295870, 2014).
pneumonia (18 papers, 2010 to 2025). An acute, acute and chronic, or chronic inflammation focally or diffusely affecting the lung parenchyma, caused by an infection in one or both of the lungs (by bacteria, viruses, fungi, or mycoplasma.). "Furthermore, the deaths are apparently not related to central defects but possibly to lung hypoventilation following pneumonia, and possibly associated with defective immunity (as reported in leptin deficient children)." (PMID 37083980, 2023). "In two patient cohorts, they could observe a positive correlation between plasma leptin levels and the risk of respiratory infection and further with mortality in patients with severe pneumonia resulting in ARDS." (PMID 33810619, 2021). "The majority of the children deficient for LEP or LEPR (55% and 38%, respectively) suffered from recurrent episodes of serious respiratory afflictions such as pneumonia and upper respiratory tract infections." (PMID 37659411, 2023). "When it comes to the possible immunoregulatory effects of leptin observed in lung injury models, one can state that leptin plays important roles in recruiting neutrophils to the airways in pneumonia models in vivo." (PMID 33816341, 2021). "An increase of leptin in lean mice plasma impairs immune responses and facilitates the infection of Klebsiella pneumoniae, resulting in increased pneumonia severity." (PMID 30832310, 2019). "Others have shown an increased neutrophil influx after leptin administration in S pneumonia induced pneumonia." (PMID 24066032, 2013). "Furthermore, the adiponectin-to-leptin ratio has emerged as a promising predictor of pneumonia severity." (PMID 41585373, 2025). "An increase of leptin, a kind of adipokine, in lean mice plasma has been found to impair immune responses and facilitate the infection of Klebsiella pneumoniae, resulting in increased pneumonia severity." (PMID 30832310, 2019). "The adiponectin/leptin ratio also significantly discriminates against COVID-19-related pneumonia, even in non-obese individuals (with BMI (body mass index) values ˂ 25 kg/m2)." (PMID 37408184, 2023). "The Xue Bi Jing Injection relieved or reduced severe pneumonia by triggering the inflammation pathway through downregulation of TNF-α, IL-6, and IL-8 on the 3rd, 7th, and 14th day after treatment, although it did not significantly influence the release of leptin." (PMID 33746739, 2020).